RNF43 (ring finger protein 43)
Diseases named in the same sentence as RNF43 in open-access papers (continued):
Sharing a sentence is not in itself a finding about the gene and the disease.
tumor (continued). "Among R-Spondins (RSPO) ligands family, RSPO2 binding to Lgr5 regulates receptor turnover through stabilization of tumor suppressors ZNFR3 and RNF43 membrane E3 ligases, that mediate ubiquitination and consequent degradation of LRP6/5 receptors." (PMID 29354056, 2017). "Ring finger protein 43 (RNF43) is a member of the transmembrane E3 ubiquitin ligase family that was originally found in stem cells and plays important roles in tumor formation and progression." (PMID 28446252, 2017). "RNF43 and BRAF are molecular events involved in the serrated tumor pathway during CRC development." (PMID 40860811, 2025). "Thus, BRAFV600E correction decreased WNT signaling activity, despite the presence of mutant RNF43, a known WNT tumor suppressor." (PMID 40687798, 2025). "To demonstrate the function of the ZNRF3/RNF43-EGFR signaling pathway in vivo, we first xenografted luciferase-labeled HT29 cells overexpressing either GFP or ZNRF3 into NSG mice by flank injection and monitored tumor growth by bioluminescence imaging." (PMID 38260423, 2024). "No RNF43 hotspot variants were observed in normal tissue, suggesting later involvement in tumorigenesis despite the very high VAF in tumor tissue." (PMID 38725616, 2024). "If tumor cells express more RNF43, the Wnt signaling pathway should be less active, since it is regulated by RNF43 via negative feedback mechanism." (PMID 36823311, 2023). "On multivariate analysis, RNF43 low/negative versus high/positive was even an independent prognosticator of survival in diffuse type GC, supporting its significant role in tumor biology." (PMID 36823311, 2023). "The expression of RNF43 and LRP1B correlated significantly with tumor type according to Lauren, i.e., both were significantly reduced in diffuse type GC, adding them to an increasing list of WNT pathway components, which are differentially mutated and expressed in diffuse and intestinal type GC." (PMID 36823311, 2023). "Of note, Rnf43/Znrf3del tumour organoids, but not WT controls, grew long-term (up to passage 10) in the absence of RSPO1, confirming their origin from Rnf43/Znrf3del cells." (PMID 35039505, 2022). "Membrane-bound E3 ubiquitin ligases RNF43 and ZNRF3 are overexpressed in colorectal cancer, and can be repurposed using proteolysis-targeting antibodies (PROTABs) to selectively degrade cell-surface receptors in tumours." (PMID 36131013, 2022). "RNF43 is a ubiquitin E3 ligase that acts as a tumor suppressor via negative modulation of the Wnt pathway by targeting the frizzled receptor." (PMID 35075588, 2022). "In addition, breaks within known tumour suppressor genes CDK12, ZNF21 and RNF43 were observed and have been shown to result in loss in function." (PMID 35396535, 2022). "However, ETV4, RNF43 and AXIN2 were clustered with tumour purity and separate from all other infiltrating cell types." (PMID 34824625, 2021). "We identify CK1 as a prominent interaction partner that binds the Ser‐rich region and phosphorylates the RNF43 tail, which promotes RNF43‐mediated tumor suppressor activity independent of FZD downregulation." (PMID 32965059, 2020). "LD tumours were also substratified into RSPO-fusion, RSPO-high and RNF43-mutant subsets." (PMID 31563876, 2020). "Twenty-three patient tumour mutations within the cytoplasmic region after the RING-finger domain, but outside the SSSDS sequence, did not alter RNF43 function in the STF-Luc reporter assay, suggesting that these are passenger mutations." (PMID 32934222, 2020). "In addition, xenografts derived from gastric RNF43 knockdown cells showed enhanced expression of the stem cell markers SOX2 and CD44, correlating with enhanced tumor growth." (PMID 30884828, 2019). "Previous in-vivo experiments revealed that RNF43 impaired tumorigenicity, and further immunohistochemical staining showed that RNF43 expression in xenograft tumor tissues had a negative correlation with β-catenin." (PMID 28446252, 2017).
tumor (continued). "In younger patients, enrichment of CTNNB1 and RNF43 mutations suggests that non-canonical WNT activation may contribute more prominently to EOCRC, potentially driving more aggressive tumor biology and earlier onset of disease." (PMID 40940930, 2025). "Therefore, we established intestinal tumor organoids using the intestinal polyps from the Apcmin mice and supplemented RSPO1 in the organoid culture medium to investigate the effect of ZNRF3/RNF43 deactivation on organoid growth and EGFR." (PMID 38260423, 2024). "In addition, there is a lack of experimental validation for the predicted roles of RNF43 in mediating the tumor immune microenvironment." (PMID 37848933, 2023). "However, a comprehensive investigation of RNF43 is lacking, and the functions of RNF43 in modulating the tumor immune microenvironment and predicting the immunotherapeutic efficacy need to be answered." (PMID 37848933, 2023). "However, lower effect magnitudes were not universal as inactivation of Rnf43 or Fbxw7 increased tumor growth as much or more in Braf;Cas9 mice than in G12C;Cas9 mice." (PMID 37828026, 2023). "Survival analysis of the intestinal type GCs showed that RNF43 low/negative GCs tended to have a better outcome compared with RNF43 high/positive GCs [24.5 months overall survival (OS) and 25.0 months tumor-specific survival (TSS) vs. 14.1 months OS and 17.9 months TSS, respectively]." (PMID 36823311, 2023). "In this study, we revealed that the enrichment of CAFs was positively correlated with tumor progression and cancer stemness in RCC, furthermore, exosomal miR-181d-5p secreted by CAFs played a key role in promoting cancer stemness and RCC progression by targeting RNF43." (PMID 36319622, 2022). "However, the present results showed heterozygous monoallelic RNF43 mutations in C14 and C24 cells, indicating that biallelic inactivation of RNF43 is not necessarily required for serrated pathway tumor development." (PMID 35040131, 2022). "AXIN2 and RNF43 are negative regulators of WNT signaling that are transcriptionally activated by nuclear β-catenin, consistent with the notion that epigenetic silencing of negative regulators plays a critical role in tumor formation in ligand-dependent, APCmut– CRCs." (PMID 34873211, 2021). "ETC-159 combined with MEK inhibitor Trametinib synergistically inhibits cell cycle progression and in vivo tumor growth of RNF43-mutant PDAC, leading study authors to propose that WNT may temper excessive and potentially deleterious MAPK/ERK signaling in RNF43-mutant PDAC." (PMID 33996827, 2021). "Furthermore, a correlation between low RNF43 and PWWP2B expression and tumor recurrence was seen." (PMID 34149925, 2021). "Our recent results using mice carrying a 57 bp deletion in exon 8 of Rnf43 (Rnf43ΔEx8), confirmed an important role for RNF43 in gastric homeostasis, since mutant mice showed gastric hyperplasia, although lesions did not develop to neoplasia." (PMID 30884828, 2019). "Finally, we examined whether or not a PORCN inhibitor suppresses the tumor development of RNF43 frameshift mutant cells in PDX models." (PMID 35040131, 2022). "Furthermore, an in vivo subcutaneous tumor formation assay was employed and showed that RNF43 knockdown enhanced the growth and volume of ccRCC xenografts, while decreasing YAP alleviated the effects of RNF43 knockdown in promoting the tumorigenicity and tumor growth of ccRCC." (PMID 37304674, 2021). "For example, a phase I clinical trial combined the ring finger protein 43 (RNF43) with other peptides and showed an 83% disease stability; however, there was no reduction in tumor burden." (PMID 34199248, 2021). "Exposure to I3C diet for 2 weeks prior to AOM/DSS treatment sufficed to correct the expression of Znrf3 and Rnf43 in an AHR-dependent manner, as mice lacking Ahr in IEC did not upregulate these tumor suppressors." (PMID 30119997, 2018). "Considering RNF43 and LRP1B as tumor suppressors only, does not seem to be sufficient." (PMID 36823311, 2023).
tumor (continued). "RNF43 and LRP1B are not easy to use prognostic or predictive biomarkers in GC and might require the simultaneous analysis of several members of the Wnt signaling pathway in relation to histological tumor type." (PMID 36823311, 2023). "Interestingly Rnf43 and Znrf3 null intestinal cells did not express NOTUM, further highlighting that as well as having different sensitivities to therapies, ligand-dependent and ligand-independent tumours have differing transcriptional responses following WNT-pathway activation." (PMID 37048063, 2023).
cancer (148 papers, 2012 to 2026). A tumor composed of atypical neoplastic, often pleomorphic cells that invade other tissues. "The development and progression of various human cancer types have been associated with enhanced expression of Wnt receptors, attributed to the mutational inactivation of the ubiquitin ligases RNF43/ZNRF3." (PMID 40152621, 2026). "Within the ‘Cancer hotspots database’, 18 variants were also present in our cohort, mainly missense, with stop-gained variants observed in RNF43 and EPHA3." (PMID 41294844, 2025). "Taken together, we identify a large number of ZNRF3 mutations that activate β-catenin signaling, and better define the mode of action through which ZNRF3 and RNF43 mutations contribute to cancer formation." (PMID 39674817, 2025). "Although RING and R-Spondin domain mutations in RNF43/ZNRF3 are often considered to possess dominant-negative oncogene-like activity in cancers, our findings challenge this notion." (PMID 39674817, 2025). "The analysis of the expression pattern and mutation signature of RNF43 suggests that this gene can be reported as an important prognostic biomarker in pan-cancer." (PMID 40735046, 2025). "Using multiple cell lines and animal models, we demonstrated that loss-of-function changes of ZNRF3/RNF43 elevate EGFR signaling activity to promote cancer progression." (PMID 38260423, 2024). "In particular, the RNF43 G659Vfs*41 frameshift mutation accounts for 40–50% of all RNF43 mutations in multiple MSI-H cancer types." (PMID 38260423, 2024). "Inactivation of RNF43 enhances sensitivity to MEK inhibitors and creates synergy between drugs targeting the WNT and MEK pathways in various RNF43‐mutated cancers." (PMID 38225722, 2024). "We discovered that EGFR is the protein most negatively associated with ZNRF3/RNF43 expression using proteogenomic data of cancer patients, and that ZNRF3/RNF43 interact with EGFR and down-regulate EGFR through ubiquitination and degradation." (PMID 38260423, 2024). "Meanwhile, the expression of mutant RNF43, as well as Wnt signaling, upregulates at an accelerating rate once the positive feedback circuit activates in cancer cells carrying oncogenic RNF43 mutations (upper left)." (PMID 38383910, 2024). "On the other hand, a truncation mutation in RNF43 found in cancer patients causes increased β-catenin stabilization and enhanced Wnt signaling." (PMID 39125653, 2024). "In accordance, tissue-specific expression patterns of FZD homologues correlate with the incidence of RNF43 or ZNRF3 cancer mutations in those tissues." (PMID 38969364, 2024). "Cancer-related RNF43 mutations promote the activation of β-catenin signaling through the aberrant rise in Wnt receptors at the cell surface membrane." (PMID 39125653, 2024). "Transmembrane E3 ligases RNF43 and ZNRF3 selectively target specific Frizzled receptors to suppress WNT signalling, offering an explanation for the cancer tissue-specific distribution of RNF43 and ZNRF3 mutations." (PMID 38969364, 2024). "Preclinical studies have shown that mutations in RNF43 make Wnt-induced cancer cells susceptible to the pharmacological inhibition of Wnt signaling by porcupine." (PMID 36831448, 2023). "RNF43 mutations affecting protein function have been observed in a variety of cancers among which those of the colon, stomach, pancreas, endometrium and ovarium." (PMID 37023034, 2023). "By the investigation of RNF43 mutations on the cBioPortal database, we discovered that RNF43 possessed a high mutation rate of 4%, and truncating mutation was the most alternation type of RNF43 in pan-cancer." (PMID 37848933, 2023).
cancer (continued). "Our results first present the expression pattern and the mutation signature of RNF43, highlighting that RNF43 is an important prognostic biomarker in pan-cancer." (PMID 37848933, 2023). "Most importantly, the alteration of RNF43 was significantly associated with PFS and DSS in cancer patients, and among patients who achieved immunotherapies, RNF43-altered patients had a longer OS time." (PMID 37848933, 2023). "To further confirm the effects of RNF43 on cancer immunotherapies, we analyzed the association between RNF43 expression and the immunotherapy efficacy in these datasets that consist of cancer patients who acquired immunotherapies." (PMID 37848933, 2023). "The authors also showed that N-terminal truncating mutations in RNF43 are required to drive increased β-catenin signalling; hence, further work is needed to understand the role of G659fs RNF43 mutations in certain WNT-driven cancers." (PMID 37048063, 2023). "A recent study has presented that RNF43/ZNRF3 depletion mutation can contribute to live cancer tumorigenesis by modulating the differentiation of hepatocytes and the liver lipid metabolic state." (PMID 37848933, 2023). "RING finger protein 43 (RNF43), an E3 ubiquitin ligase, is a homologous gene mutated in several cancers." (PMID 37848933, 2023). "We further illustrated the genetic mutation characteristics of RNF43 in pan-cancer in the cBioPortal online database." (PMID 37848933, 2023). "Subsequent studies have shown WNT974 to be particularly effective in cancer models harbouring either RNF43 or RSPO mutations." (PMID 37048063, 2023). "RNF43 mutations frequently appear in these cancers, and the downregulation of RNF43 predicts a poor prognosis in patients." (PMID 36097369, 2023). "Our findings provide the characteristics of RNF43 mutations in pan-cancer for further understanding the roles of RNF43 mutations in cancer progression and treatment." (PMID 37848933, 2023). "RNF43 was frequently mutated in several cancers with a high frequency of 4%, and truncating mutation was the most frequent RNF43 mutation type." (PMID 37848933, 2023). "More studies are needed to identify cancer cell and mutant types that are sensitive to Porcupine inhibitors, as RNF43 mutations have been found in a variety of cancers such as pancreatic, stomach, ovary, and colon cancers." (PMID 35487932, 2022). "Together, these results demonstrate that RNF43 frameshift mutations retain normal functionality; thus, targeted anti-cancer therapy can be developed according to the mutation type of RNF43." (PMID 35487932, 2022). "Cancer genomic studies have identified RNF43 and ZNRF3 as WNT pathway genes mutated in liver cancer." (PMID 35039505, 2022). "Inactivation of RNF43 through RNF43 mutations can lead to permanent activation of Wnt pathway in cancer cells." (PMID 35907983, 2022). "Given the relationship between TET1 and clinical outcome, we next conducted a similar analysis using RNF43, the gene with the second strongest association with vital status in the pan-cancer cohort." (PMID 35798829, 2022). "Another gene found mutated in cancer patients is the RNF43 (Ring Finger Protein 43), a downstream target gene of Wnt/b catenin signaling." (PMID 35158934, 2022). "In cancer cells, Wnt signalling is activated through loss of function of RNF43 via mutations, leading to a decrease in the degradation of Frizzled." (PMID 36866106, 2022). "The loss of Wnt/β-catenin activity seen in the existing RNF43/EP300-mutant cancer cell lines is likely due to the loss of any selective pressure to maintain Wnt signaling in these cells once p300 is mutated." (PMID 35536676, 2022).